HMGN1 (high mobility group nucleosome binding domain 1)
Diseases named in the same sentence as HMGN1 in open-access papers (continued):
Sharing a sentence is not in itself a finding about the gene and the disease.
tumor (continued). "In addition, HMGN1 controls the transcription process of some oncogenes and tumor suppressor genes involved in tumor progression, mainly suppressing the development of cancer." (PMID 26444668, 2015). "In addition, HMGN1 was found to be involved in regulating the tumor microenvironment." (PMID 38310387, 2025). "Hence HMGN1 has been harnessed to promote generation of antitumor immune responses as DNA vaccines or in combination with chemotherapeutic agents and activators/checkpoint inhibitors in different tumor models." (PMID 32286296, 2020). "However, it remains to be established whether systemic administration of HMGN1 also influences anti-tumor T cell responses." (PMID 30696484, 2019). "Collectively, these results suggest that combination of αCD4 and low-dose HMGN1 (in the range of 0.08 to 0.4 μg per injection), brings T-cell dependent anti-tumor effects in mouse subcutaneous tumor models and has an ability to develop immunological memory against tumor cells." (PMID 30696484, 2019). "However, the exact function of HMGN1 in various tumor types is still unknown." (PMID 38310387, 2025). "The expression of HMGN1, HSP90AA1, BCL2, and AGER was verified in TCGA and GTEx databases, and HMGN1, HSP90AA1 and AGER were found to be highly expressed in tumor tissues." (PMID 38713284, 2024). "Similar anti-tumor effects were observed in the combination therapy of αCD4 with human HMGN1 in Colon26-bearing mice, suggesting that human HMGN1 might share the similar structure and function with murine HMGN1, and might have cross-species activity in its anti-tumor effects." (PMID 30696484, 2019). "The HMGN1/αCD4 treatment expanded effector CD8+ T cells and prolonged their anti-tumor activities by rescuing them from exhaustion, thus resulting in tumor regression and even rejection in long-term monitored mice." (PMID 30696484, 2019). "In this study, we evaluated the anti-tumor effects and immunological responses induced by co-administration of HMGN1 and anti-CD4 depleting antibody intraperitoneally in Colon26 or B16F10 tumor-bearing mice." (PMID 30696484, 2019). "HMGN1 is a TLR4 ligand that enhances Th1 immune responses and induces prophylactic anti-tumor immunity." (PMID 28881713, 2017). "Hepa1-6 tumor bearing mice after three rounds of treatment with HMGN1, R848 and anti-CTLA4 showed significantly increased infiltration of CD3+, CD4+, and CD8+ T cells in tumor tissues." (PMID 28881713, 2017). "Here, we developed an immunotherapeutic regimen capable of eliminating large established mouse tumors using HMGN1, a DC-activating TLR4 agonist capable of inducing anti-tumor immunity." (PMID 29079801, 2017). "Thus, we have developed a curative therapeutic vaccination regimen dubbed ‘TheraVac’ consisting of HMGN1 and R848 plus a checkpoint inhibitor, that can, without using exogenous tumor-associated antigen(s), eliminate various large tumors and induce tumor-specific immunity." (PMID 29079801, 2017). "We observed that HMGN1 were highly expressed in LUAD tissues compared with normal tissues at the RNA and protein level, while HMGN3/5 were expressed at a lower level in the tumor tissues compared to normal controls." (PMID 38710740, 2024). "Absence of tumor specific immune response in Hmgn1−/− mice and increased anti-tumor immune response, when vaccinated mice with DNA vector overexpressing HMGN1, provide further support the role of HMGN proteins in regulating immune cell function and response." (PMID 31936777, 2020). "To determine the effect of DCTEX-N1ND on the tumor microenvironment, we examined CD8+ T cells in blood and tumor tissues from day-21 orthotopic HCC mice treated with DCTEX-N1ND as DCTEX and HMGN1 were shown to function primarily via stimulation of CD8+ T cells and increased IFN-γ secretion." (PMID 32286296, 2020). "All these findings indicate that lack of endogenous HMGN1 is likely to contribute to tumor progression." (PMID 30696484, 2019).
tumor (continued). "Our results demonstrate that the combined treatment with low-dose HMGN1 and anti-CD4 depleting antibody exerts synergistic anti-tumor effects by promoting CD8+ T cell activation, expansion, and by counteracting exhaustion of activated CD8+ T cells in the tumor." (PMID 30696484, 2019). "Collectively, these results suggested that the HMGN1/αCD4 treatment reduces the level of co-inhibitory molecules in these exhausted CD8+ T cells, increases their effector functions, and decreases the proportion of exhausted CD8+ T cells in the tumor." (PMID 30696484, 2019). "In addition, treatment with HMGN1 and R848 increased CTLs in the draining LNs and upregulated chemokines CXCL9 and CXCL10, as well as IFN-γ, all indicators of Th1 immunity in the tumor tissue." (PMID 28881713, 2017). "In a novel in situ strategy, another group of investigators achieved robust anti-tumor response in the 4T1 breast cancer model by pulsing dendritic cells with tumor-cell derived exosomes that were fused with the DAMP, nucleosome-binding protein 1 (HMGN1; TEX-N1ND)." (PMID 32937885, 2020). "The only disadvantage is the need to deliver R848 and HMGN1 into the tumor tissues, which may not be easily translated into use on inaccessible tumors." (PMID 28881713, 2017). "The only drawback is the need to inject R848 and HMGN1 into the tumor tissues, which may not be easily accessible for tumors in deep organs." (PMID 29079801, 2017). "Moreover, Hmgn1−/− mice without endogenous HMGN1 displayed lower number of CD8+ T cells and higher tumor growth rate relative to Hmgn1+/+ mice." (PMID 30696484, 2019).
cancer (15 papers, 2009 to 2025). A tumor composed of atypical neoplastic, often pleomorphic cells that invade other tissues. "Pan-cancer analysis revealed that HMGN1 was upregulated in several solid tumors and was associated with pathological staging and poor prognosis." (PMID 38310387, 2025). "Additionally, gene co-expression analysis was employed to study the correlation between the genes associated with the immune system and HMGN1 expression levels in 33 cancers, such as chemokines, MHC-encoding genes, chemokine receptors, immune-activating, and immune-suppressing genes." (PMID 38310387, 2025). "Here, we examined the involvement of the HMGN1 gene in cancer prediction, progression, and treatment by thoroughly analyzing the HMGN1 gene molecular signature in 33 types of cancers, derived from multiple portals such as the TCGA, GTEx, and UALCAN." (PMID 38310387, 2025). "Thereafter, the pan-cancer analysis was implemented to understand the HMGN1 expression patterns, prognostic value, and immunological features." (PMID 38310387, 2025). "The HMGN1 levels and OS of the pan-cancer patients in the TCGA database were examined using Cox proportional risk models." (PMID 38310387, 2025). "Based on the data derived from the TCGA and GTEx databases, our findings implied that HMGN1 was significantly overexpressed in 26 types of cancers in comparison to the normal tissues." (PMID 38310387, 2025). "According to ESTIMATE scores, the stromal and immune cell concentrations were inversely related to the HMGN1 expression in the TIME of 8 types of cancers." (PMID 38310387, 2025). "The HMGN1 expression in different types of cancers and its potential use in cancer diagnosis and prognosis were investigated during this study using a variety of bioinformatics methodologies." (PMID 38310387, 2025). "Firstly, the HMGN1 expression levels in different forms of cancers were analyzed and ranked from high expression to low expression levels." (PMID 38310387, 2025). "Except for the tumors without appropriate normal sample data, significant variations were noted in the HMGN1 expression levels presented by the malignant and normal tissues in 18 cancers." (PMID 38310387, 2025). "The findings of the correlation study between HMGN1 levels and TMB/MSI revealed that TMB was linked to HMGN1 expression in 14 cancers, while MSI was associated with HMGN1 expression in 16 types of cancers." (PMID 38310387, 2025). "The findings revealed that HMGN1 exhibits elevated expression levels in diverse cancer types, indicating its potential as a promising biomarker for predicting prognosis." (PMID 38310387, 2025). "In this study, we show that TEX-N1ND is effective irrespective of the endogenous HMGN1 expression in tumors and it seems that it works better in tumors with low HMGN1 expression, which is loosely correlated to staging of cancer." (PMID 32286296, 2020). "A proteomics study in HMGN1 knockout revealed the role of HMGN1 in complement and coagulation cascade and interferon response in cancer cells, reinforcing the role of HMGN1 in regulating immune response." (PMID 31936777, 2020). "shRNAs targeting HMGN1 were selectively depleted in AML cells compared to all other cancer cell types, suggesting a lineage-specific dependency on HMGN1 in AML." (PMID 32179749, 2020). "The correlation between cancer tissue expressed HMGB1/HMGN1 and stromal immune cell infiltrate were then observed." (PMID 30619746, 2018). "Initially, HMGNs were regarded as transcription coregulators, however, their roles in DNA repair and cancer progression have been determined using HMGN1 knockout mice." (PMID 24348831, 2014). "In summary, HMGN1 was strongly expressed in the majority of cancers." (PMID 38310387, 2025). "Since HMGN1 was linked to OS, DFS, DSS, and PFS in both LIHC and ACC, HMGN1 was integrated with clinicopathological variables in ACC and LIHC to develop predictive nomograms for cancer patients." (PMID 38310387, 2025).
cancer (continued). "Furthermore, the HMGN1 expression levels in the malignant and healthy samples derived from 33 forms of cancers were also compared using the TCGA dataset." (PMID 38310387, 2025). "This study highlighted the potential of HMGN1 as a biomarker for pan-cancer analysis." (PMID 38310387, 2025). "Additionally, enrichment analyses were implemented to assess the biological roles of HMGN1 in various types of cancers." (PMID 38310387, 2025). "Additionally, numerous studies have demonstrated that HMGN1 enhances anticancer immunity by reversing T-cell depletion and increasing the response of malignant cells to cancer vaccines." (PMID 38310387, 2025). "Finally, the GDSC database was employed for assessing the connection between HMGN1 expression levels and drug sensitivity of various medications for different cancers, offering a theoretical foundation for clinical use." (PMID 38310387, 2025). "Notably, GSEA analyses of HMGN1 in several other cancer types have also emphasized the essential roles of HMGN1 in DNA repair (Supplementary 3B–E and G)." (PMID 38710740, 2024). "However, the specific function of HMGN1 in cancer development is unclear." (PMID 38310387, 2025). "Therefore, the relationship between TIME and HMGN1 was assessed and the ESTIMATE algorithm was employed for assessing the stromal and immune scores in the malignant tumors." (PMID 38310387, 2025).
neurodevelopmental disorder (3 papers, 2015 to 2023). A behavioral and cognitive disorder with onset during the developmental period that involves impaired or aberrant development of intellectual, motor, or social functions. "Altogether, these studies emphasize the importance of non-neuronal and non-cerebral cortex cell types in neurodevelopmental disorders, in which the vertebrate-specific Hmgn1 and related proteins may play a unifying role by regulating chromatin accessibility for key transcription factors." (PMID 37191016, 2023).
neurological disease (2 papers, 2014 to 2022). "Although altered HMGN1 expression has been linked to neurological disorders, it is not clear whether the neurological phenotypes seen in DS individuals are caused by elevated HMGN1 levels." (PMID 36463299, 2022).
infection (1 paper, 2018). The state of being infected such as from the introduction of a foreign agent such as serum, vaccine, antigenic substance or organism. "In conclusion, HMGN1 is an endogenous TLR4 ligand that can induce both acute stimulation of cytokine production and long-term tolerance, and thus it might play a modulatory role in sterile inflammatory processes such as those induced by infection, trauma, or ischemia." (PMID 29593748, 2018).
HMGN1 also shares sentences with these, for which no sentence is quoted: acute lymphoblastic leukemia (2 papers); Alzheimer disease (2); autoimmune disease (2); glioma (2); liver cancer (2); aging (1); cognitive deficits (1); colon cancer (1); colorectal cancer (1); hematologic malignancies (1); Insulin resistance (1); leiomyosarcoma (1); Lewis Lung Carcinoma (1); lymphoma (1); mesothelioma (1); neuroblastoma (1); Obesity (1); ovarian carcinoma (1); pancreatic cancer (1); papillary renal cell carcinoma (1); rectum adenocarcinoma (1); schizophrenia (1); stomach cancers (1); systemic sclerosis (1); trisomy 21 (1); type 2 diabetes (1); virus infection (1); Wilms tumor (1).